GADD45GIP1 (GADD45G interacting protein 1)
Description:
Acts as a negative regulator of G1 to S cell cycle phase progression by inhibiting cyclin-dependent kinases. Inhibitory effects are additive with GADD45 proteins but also occur in the absence of GADD45 proteins. Acts as a repressor of the orphan nuclear receptor NR4A1 by inhibiting AB domain-mediated transcriptional activity. May be involved in the hormone-mediated regulation of NR4A1 transcriptional activity. May play a role in mitochondrial protein synthesis.
Synonyms: MRP-L59; CRIF1; PLINP; PLINP-1; PLINP1; PRG6; MGC4667; MGC4758; CKBBP2; CKbetaBP2; mL64
Tractability: Small molecule: a structure with a bound ligand is known. PROTAC: ubiquitination databases record sites on it; its protein half-life has been measured.
Gene: Protein-coding gene on chromosome 19 (12,953,119 to 12,957,223, reverse strand). Ensembl gene ENSG00000179271.
Subcellular location: Mitochondrion; Nucleus
Subcellular location (Human Protein Atlas): Mitochondria
Pathways (Reactome):
Metabolism of proteins: Mitochondrial ribosome-associated quality control; Mitochondrial translation elongation; Mitochondrial translation initiation; Mitochondrial translation termination
Gene Ontology:
Molecular function: protein binding; structural constituent of ribosome
Biological process: mitochondrial translation
Cellular component: mitochondrial large ribosomal subunit; mitochondrial matrix; mitochondrion; nucleus; mitochondrial inner membrane
Genetic constraint (gnomAD): Loss-of-function variants: 17 observed, 19.38 expected, observed/expected ratio (o/e) 0.88, 90% interval 0.6 to 1.32. The upper end of that interval is the gene's LOEUF score, 1.32, which puts it in group 5 of 6, group 1 being the genes least tolerant of losing a copy. Missense variants: 294 observed, 265.48 expected, observed/expected ratio (o/e) 1.11, 90% interval 1.01 to 1.22. Synonymous variants: 135 observed, 112.39 expected, observed/expected ratio (o/e) 1.2, 90% interval 1.04 to 1.39.
Homologues: Orthologues: chimpanzee GADD45GIP1 (99% identical), macaque GADD45GIP1 (93% identical), guinea pig GADD45GIP1 (82% identical), dog GADD45GIP1 (80% identical), pig GADD45GIP1 (80% identical), rat Gadd45gip1 (75% identical), mouse Gadd45gip1 (74% identical), rabbit GADD45GIP1 (73% identical), tropical clawed frog gadd45gip1 (41% identical), zebrafish gadd45gip1 (37% identical), Drosophila melanogaster CRIF (26% identical), Caenorhabditis elegans K07A1.10 (19% identical).
Diseases named in the same sentence as GADD45GIP1 in open-access papers:
GADD45GIP1 is named in the same sentence as 54 diseases in open-access papers, as found by Europe PMC text mining. Sharing a sentence is not in itself a finding about the gene and the disease. The quoted sentences say what the papers report.
ovarian carcinoma (1 paper, 2019). A malignant neoplasm originating from the surface ovarian epithelium. "Second, we further investigated regulation of the MAPK pathway by the NAC‐1/Gadd45gip1/Gadd45 pathway following treatment of ovarian cancer cells with CRM197." (PMID 31490008, 2019). "We also found that NAC‐1 activates the proapoptotic JNK/p38MAPK pathway, resulting in apoptosis and induction of resistance to paclitaxel by modulating its downstream pathway, Gadd45gip1/Gadd45, in ovarian cancer cells." (PMID 31490008, 2019). "CRM197 treatment sensitized the paclitaxel‐resistant ovarian cancer to paclitaxel, at least in part, via NAC‐1 and its downstream Gadd45gip1/ Gadd45 pathway in A2780/Taxol and SKOV3/Taxol cells." (PMID 31490008, 2019). "First, we investigated the role of nucleus accumbens‐1 (NAC‐1) and its downstream pathway, growth arrest and DNA damage‐inducible 45‐γ interacting protein (Gadd45gip1)/growth arrest and DNA damage‐inducible 45 (Gadd45), in CRM197‐mediated reversal of paclitaxel resistance in ovarian cancer cells." (PMID 31490008, 2019). "In this study, we analyzed the mechanism of reversion of paclitaxel resistance by CRM197 and identified a signaling axis involving NAC‐1/Gadd45gip1/Gadd45γ, which appears to enhance activities of the proapoptotic JNK/p38MAPK pathway that induces paclitaxel resistance in ovarian cancer." (PMID 31490008, 2019).
tumor (16 papers, 2015 to 2026). "Further, the expression of NDUFB7, AURKAIP1, ROMO1, SCAND1, GADD45GIP1, and NDUFA13 was upregulated in the four tumor subtypes compared with normal adjacent tissue." (PMID 34996995, 2022).
GADD45GIP1 also shares sentences with these, for which no sentence is quoted: cancer (8 papers); hepatocellular carcinoma (6); cardiovascular diseases (5); diabetes (5); endothelial dysfunction (5); Insulin resistance (5); leukemia (5); breast carcinoma (4); osteosarcoma (3); type 2 diabetes (3); acute myeloid leukemia (2); Alzheimer disease (2); cardiac hypertrophy (2); cardiomyopathy (2); fibrosis (2); Glomerular sclerosis (2); Glucose intolerance (2); inflammation (2); keloid (2); lupus (2); Obesity (2); prostate carcinoma (2); viral infection (2); albuminuria (1); atherosclerosis (1); atrial fibrillation (1); blood disease (1); cardiac diseases (1); Chronic colitis (1); colitis (1).
A further 22 diseases each share a sentence with GADD45GIP1 in 1 paper.